PTPRO (protein tyrosine phosphatase receptor type O)
Diseases named in the same sentence as PTPRO in open-access papers (continued):
Sharing a sentence is not in itself a finding about the gene and the disease.
breast carcinoma (continued). "We performed bisulfite genomic sequencing from ten pairs of breast tumor tissue and matched normal tissue, one representative HMEC (48R), and one breast cancer cell line (MCF-7) to determine if the CpG Island located in the promoter of PTPRO was differentially methylated." (PMID 24919593, 2014). "Two hundred twenty-one formalin-fixed, paraffin-embedded (FFPE) tumor tissues, 20 FFPE normal adjacent tissues and 24 matched plasma samples, collected from primary breast cancer patients, were assessed for PTPRO gene promoter methylation using methylation-specific PCR." (PMID 24090193, 2013). "PTPRO methylation is associated with unfavorable survival in patients with HER2-positive breast tumors, and therefore can serve as a potential prognostic factor for breast cancer." (PMID 24090193, 2013). "Therefore, the specific objective in this study was to better characterize the clinical relevance of PTPRO methylation in breast cancer." (PMID 24090193, 2013). "We examined the methylation status of the PTPRO gene promoter in breast cancer and evaluated the correlation between PTPRO promoter methylation and both clinicopathological parameters and prognosis of breast cancer patients." (PMID 24090193, 2013). "Thus, the precise downstream effects of PTPRO methylation in the carcinogenesis and progression of breast cancer deserves further exploration." (PMID 24090193, 2013). "Therefore, strengthening PTPRO or targeting PTPRO-mediated pathways could be potential strategies for inhibiting breast cancer lung metastasis." (PMID 40016288, 2025). "In the current study, we showed that low expression of PTPRO is associated with poor prognosis and PTPRO could serve as an independent prognostic factor for relapse-free survival for patients with ERBB2-enriched breast cancer." (PMID 35431974, 2022). "However, little is known about PTPRO’s role in the immunotherapy response in breast cancer." (PMID 36003382, 2022). "Furthermore, immunoblotting demonstrated that PTPRO was enriched in exosomes derived from PTPRO overexpressing cells, indicating that PTPRO could be encapsulated in exosomes delivered from breast cancer cells." (PMID 34650968, 2021). "Additionally, detection of PTPRO methylation in peripheral blood of breast cancer patients may provide a noninvasive means to diagnose and monitor the disease." (PMID 24919593, 2014). "Both in vitro and in vivo data demonstrated that PTPRO inactivates the JAK2–YAP pathway and diminishes the metastatic ability of breast cancer." (PMID 40016288, 2025). "In the case of breast cancer, PTPRO promoter methylation is a prognostic factor for HER2-positive patients and suppresses ERBB2-driven breast cancer growth by promoting ERBB2 dephosphorylation and endocytotic degradation." (PMID 38182570, 2024). "Two established lapatinib resistant ERBB2-positive breast cancer cells, SKBR3-lapR and BT474-lapR, were transfected with the plasmid overexpressing PTPRO." (PMID 35431974, 2022). "In this study, we explored the correlation between PTPRO and lapatinib resistance in ERBB2-positive breast cancer." (PMID 35431974, 2022). "We found that 1) reduced levels of PTPRO correlate with poorer clinical outcomes; and 2) overexpressed PTPRO in lapatinib resistant ERBB2-positive breast cancer cells is capable of reversing lapatinib-resistance." (PMID 35431974, 2022). "In this study, we provide evidence that PTPRO as a potential immune indicator and PTPRO-related CD8+ T-cell signatures (PTSs) can be used to predict prognosis and immunotherapy response in breast cancer patients." (PMID 36003382, 2022). "Our findings suggest that PTPRO is not only able to serve as an independent prognostic indicator, but upregulating PTPRO can also reverse the lapatinib resistance of ERBB2-positive breast cancer." (PMID 35431974, 2022).
breast carcinoma (continued). "Besides, downexpression of PTPRO in epithelial cells attributes to promoter methylation in multiple types of cancers, including hepatocellular carcinomas (HCC), breast cancer, lung cancer and esophageal cancer, suggesting that PTPRO may be a candidate target for tumor epigenetic therapy." (PMID 34880876, 2021). "Further supporting our claim is work from another group showing that the receptor tyrosine kinase ErbB2/HER2 is a direct substrate of PTPRO, and low levels of PTPRO expression correlated with reduced survival of HER2-positive breast cancer patients." (PMID 24919593, 2014). "Moreover, given that CRCI is highly prevalent in women with breast cancer and females are more vulnerable to CRCI, we deliberately focused on the ameliorative effects of PTPRO on DOX-induced CRCI in female mice." (PMID 37485875, 2023). "To understand the protective role of PTPRO in CRCI, we selected administration of doxorubicin (DOX), which is one of the most active agents for treatment of breast cancer, once a week for 4 weeks to induce a CRCI model in 3-month-old Ptpro+/+ and Ptpro–/– female mice." (PMID 37485875, 2023). "Furthermore, we performed the IHC staining assay to analyze PTPRO and CD8 expression in 30 human breast cancer tissues." (PMID 36003382, 2022). "Since PTPRO expression is closely related to ERBB2 status, we thus further investigated the relationship between PTPRO expression and clinical outcomes in ERBB2-stratified breast cancer patients in a large dataset." (PMID 35431974, 2022). "PTPRO methylation was observed in 53 of 98 (54%) breast cancer tissues but not in adjacent normal tissue." (PMID 24919593, 2014). "Primary survival analysis of the entire cohort reveals no prognostic value for PTPRO methylation in breast cancer patients in general." (PMID 24090193, 2013). "Nevertheless, to our knowledge no studies have investigated the prognostic value per se of PTPRO gene promoter methylation in patients with primary breast cancer." (PMID 24090193, 2013). "Moreover, this assay appears to be robust and highly specific; no methylated PTPRO was detected in plasma from breast cancer patients without primary tumor methylation or from normal healthy control peripheral blood samples." (PMID 24919593, 2014). "Furthermore, downregulation of PTPRO by aberrant hypermethylation in various cancer types, including lung cancer, hepatocellular carcinoma (HCC), breast cancer, esophageal cancer, and leukemia, suggests that it may be a therapeutic candidate for epigenetic therapy." (PMID 36003382, 2022). "In normal mammary epithelial cells, PTPRO is expressed at appreciable levels and its promoter region is not methylated; in contrast, PTPRO expression was relatively low in two (MCF-7, MDA-MB-231) of the three breast cancer cell lines examined and its promoter was methylated." (PMID 24919593, 2014).
hepatocellular carcinoma (12 papers, 2015 to 2025). A malignant tumor that arises from hepatocytes. "Moreover, PTPRO-mediated autophagy inhibits tumorigenesis in hepatocellular carcinoma (HCC), and PTPRO downregulation is associated with an IL-6-driven increase in PD-L1 expression in monocytes and macrophages." (PMID 38182570, 2024). "The methylation levels of the PTPRO gene have been studied in the pathobiology of several neoplasms including hepatocellular cancer and various lung tumors, with indications of potential tumor suppressor features." (PMID 38435839, 2024). "A most recent study has shown that increased serum IL-6 downregulated PTPRO expression in human hepatocellular carcinoma (HCC) monocytes and macrophages." (PMID 34650968, 2021). "The results confirmed increased frequencies of PTPRO hypermethylation in the hepatocellular carcinoma samples that express CT-RERG." (PMID 34462486, 2021). "Expression of PTPRO mRNA was confirmed after the transplanted hepatoma was treating with 5-azacytidine." (PMID 29558404, 2018). "We have previously demonstrated that PTPRO represses development of hepatocellular carcinoma by down-regulation of STAT3 (signal transducers and activators of transcription 3)." (PMID 25826083, 2015). "It has also been suggested that male-specific susceptibility to hepatocellular carcinoma is due to female protection via estrogen-mediated inhibition of IL-6 expression, as well as direct inhibition of STAT3 via estrogen-mediated expression of the tyrosine phosphatase PTPRO." (PMID 39689092, 2024). "The aim of the present study was to investigate the relationship between decreased PTPRO and increased programmed death ligand 1 (PD-L1) in both the peripheral monocytes and tumor-infiltrating macrophages of human hepatocellular carcinoma (HCC)." (PMID 32581055, 2020). "Moreover, PTPRO dephosphorylated JAK2 and downregulated JAK2/STAT3 signaling in hepatocellular carcinoma." (PMID 38182570, 2024). "Moreover, in hepatocellular carcinoma, increased IL-6 activated the STAT3/c-MYC/miR-25-3p pathway, which resulted in the decreased protein tyrosine phosphatase receptor type O (PTPRO)." (PMID 33413496, 2021).
colorectal cancer (8 papers, 2014 to 2025). A primary or metastatic malignant neoplasm that affects the colon or rectum. "Research in colorectal cancer has revealed that PTPRO can associate with erb-b2 receptor tyrosine kinase 2 (ERBB2), thereby inhibiting signaling pathways and obstructing tumor growth." (PMID 38999976, 2024). "Upregulating PTPRO expression in tumors, such as esophageal squamous cell carcinoma, breast, and colorectal cancers, has tumor-suppressive effects by preventing tumor growth and metastases." (PMID 38999976, 2024). "For example, the protein tyrosine phosphatase receptor type O inhibits the tumorigenesis and progression of colorectal cancer by modulating the metabolism of fatty acids." (PMID 39588377, 2024). "Down-regulation of PTPRO mRNA expression strongly correlates with a poor patient prognosis, highlighting the contribution of PTPRO to colorectal cancer development and progression." (PMID 25301722, 2014). "Taken together, these results indicate that PTPRO controls of the MAPK signaling pathway in colorectal cancer cells by regulating SRC activity." (PMID 25301722, 2014). "Our previous results indicate that protein tyrosine phosphatase receptor type O (PTPRO) is down-regulated in a subset of colorectal cancer (CRC) patients with a poor prognosis." (PMID 25301722, 2014). "For example, PTPRO inhibits colorectal cancer liver metastasis by dephosphorylating AKT and MAPK26." (PMID 40016288, 2025). "Besides, PTPRO is a candidate tumor suppressor in human lung cancer and down-regulation of PTPRO mediated by miR-6803-5p promotes the proliferation and invasion of the cancer cells in colorectal cancer." (PMID 35906634, 2022). "Since cetuximab is clinically more relevant to colorectal cancer patients, we also examined whether of PTPRO expression levels affect the response to cetuximab." (PMID 25301722, 2014). "In the patients with colorectal cancer (CRC) and poor prognosis, protein tyrosine phosphatase receptor type O (PTPRO) exhibits downregulation." (PMID 39130630, 2024).
glomerular diseases (6 papers, 2012 to 2025). "The genes FN1, and PTPRO were reported by the Online Mendelian Inheritance in Man (OMIM) database to be associated with glomerulopathy, renal fibrosis and nephrotic syndrome, respectively." (PMID 34557161, 2021). "Nephrin, podocin, synaptopodin, podocalyxin, CD2AP, ACTN4 (encodes for α-actinin 4), PTPRO (encodes for GLEPP-1), and WT1 mRNA have been isolated from urine of patients with varying glomerulopathies." (PMID 24327929, 2013).
diabetic nephropathy (5 papers, 2013 to 2023). "The below cutoff expression (represented in transcripts per kilobase million or TPM) of PTPRO could represent any of the three diseased conditions such as early diabetic nephropathy, glomerular and tubular diabetic kidney diseases." (PMID 34557161, 2021). "Under expression of PTPRO and KNG1 with fold change of -3.308 and -1.618 respectively were reported in diabetic nephropathy in comparison with healthy living donors." (PMID 34557161, 2021).
lung carcinoma (5 papers, 2021 to 2024). "Markedly, overexpression of PTPRO was associated with poorer prognosis in five type cancers, which included blood, brain, breast, esophagus and lung cancers." (PMID 35003364, 2021). "Specifically, downregulation of PTPRO was observed in lung cancer, including adenocarcinoma and squamous cell carcinoma." (PMID 38182570, 2024). "In the lungs, the role of PTPRO has only been reported in human lung cancer." (PMID 35906634, 2022).
preeclampsia (5 papers, 2018 to 2025). Preeclampsia is a hypertensive disorder of pregnancy that is characterized by new-onset hypertension with proteinuria presenting after 20 weeks of gestation, and depending on mild or severe forms may initially present with severe headache, visual disturbances, and hyperreflexia. "miRNA-548c -5p prevents preeclampsia by targeting the PTPRO gene and blocking the NF-κB signaling pathway to reduce the inflammatory response." (PMID 40104134, 2025). "PTPRO is up-regulated in placental mononuclear cells in patients with preeclampsia and its down-regulation mediated by miR-548c-5p overexpression plays an anti-inflammatory role in preeclampsia." (PMID 35906634, 2022). "In our previous study, PTPRO has been demonstrated to be significantly upregulated in preeclampsia patients, which is also found to be involved in regulating macrophage inflammation in preeclampsia." (PMID 34007244, 2021). "A previous study suggests that PTPRO may contribute to inflammatory response in preeclampsia." (PMID 35906634, 2022).
breast tumors (4 papers, 2013 to 2025). "The rather high frequency of methylation suggests that PTPRO is a common target for epigenetic silencing in breast tumors and that it may contribute to the development of this tumor type." (PMID 24919593, 2014). "Positive associations with nodal involvement, poorly differentiated histology, and HER2 amplification indicate that PTPRO methylation may contribute to an aggressive breast tumor phenotype." (PMID 24919593, 2014). "The significant associations between PTPRO methylation and nodal involvement, poorly differentiated histology, stage III tumors, and HER2 amplification suggest that PTPRO expression may be involved in breast tumor invasion." (PMID 24919593, 2014).
nephrotic syndrome (4 papers, 2021 to 2025). A collection of symptoms that include severe edema, proteinuria, and hypoalbuminemia; it is indicative of renal dysfunction. "Expression of this receptor tyrosine phosphatase in podocytes provides a rationale why PTPRO mutations are causative of childhood-onset nephrotic syndrome." (PMID 36755664, 2022). "Nephron functionality apparently is very vulnerable because many different podocyte-related genes have been uncovered as monogenetic cause of nephrotic syndromes, and mutant PTPRO alleles are regularly detected, although this could be population dependent." (PMID 36755664, 2022).
Obesity (4 papers, 2015 to 2024). Accumulation of substantial excess body fat. "Protein tyrosine phosphatase receptor type O (PTPRO) was identified as strongly associated with sweetness preference, indicating a positive correlation between sweetness preference and obesity risk." (PMID 39275286, 2024). "Collectively, evidence confirmed that PTPRO deletion promotes obesity-related hyperinsulinemia and autophagy deficiency in the liver." (PMID 36660927, 2023). "Taken together, these observations confirm that PTPRO deletion promotes obesity-mediated hyperinsulinemia and autophagy deficiency in the liver." (PMID 25826083, 2015). "Although the heterogeneity (I2) for rs1457538 is relatively high, the expression of PTPRO may contribute to the risk of obesity, implying a positive correlation between sweetness preference and obesity risk." (PMID 39275286, 2024). "Since PTPRO is involved in the regulation of glucose and lipid metabolism and the inactivation of the insulin receptor, this further suggests a positive correlation between sweetness preference and obesity risk." (PMID 39517154, 2024). "The gene encoding protein tyrosine phosphatase receptor type O (PTPRO), which is upregulated in adipose tissue due to obesity and obesity-induced inflammation, has been strongly associated with sweetness preference." (PMID 39517154, 2024). "The roles of PTPRO have been reported to involve the control of glucose and lipid metabolism, obesity-induced systemic inflammation, and the inactivation of the insulin receptor." (PMID 39275286, 2024). "PTPRO deletion significantly augmented obesity-reduced autophagy, as evidenced by increased p62 expression and a reduced LC3II/I ratio, as revealed by western blotting." (PMID 36660927, 2023). "PTPRO regulates autophagy and lipid metabolism in obesity and steatohepatitis." (PMID 36660927, 2023). "Furthermore, PTPRO regulates lipid metabolism through reduced expression of lipogenesis genes and induction of β-oxidation-related gene expression, and obesity significantly induces tumorigenesis in the liver in ptpro−/− mice." (PMID 36660927, 2023). "Our results showed that obesity significantly reduced autophagy, furthermore, PTPRO deletion could aggravate it, as evidenced by a reduced LC3II/I ratio and increased p62 expression when analyzed by western blot." (PMID 25826083, 2015). "Our data indicate that PTPRO may regulate autophagy and lipid metabolism in the context of obesity and steatohepatitis." (PMID 25826083, 2015). "To investigate whether PTPRO contributes to steatosis and tumorigenesis, we used a NASH-HCC animal model to monitor progression from obesity to HCC according to the method reported by Park." (PMID 25826083, 2015).